PLK1 (polo like kinase 1)
Diseases named in the same sentence as PLK1 in open-access papers (continued):
Sharing a sentence is not in itself a finding about the gene and the disease.
prostate carcinoma (continued). "Previous study showed that PLK1 was upregulated in prostate cancer cell, and necroptosis regulated by inhibition of PLK1 might be an effective intervention for castration-resistant prostate cancer." (PMID 36101745, 2022). "As PLK1 plays a critical role in the proliferation of cells, centrosome abnormalities, mediation of the cell cycle and apoptosis, it is considered a potential treatment target in prostate cancer." (PMID 33632199, 2021). "Overall, these observations point to the possibility that inhibitors to PLK1 (and related kinases) may help suppress prostate cancer metastasis." (PMID 34680307, 2021). "However, numerous studies indicate that PLK1 can act as an oncogene, and PLK-1 inhibitors can effectively inhibit prostate cancer progression." (PMID 33197890, 2020). "Moreover, downstream pathways regulated by PLK1 comprised the single largest pathway group in our biochemical recurrence prediction model for prostate cancer." (PMID 33197890, 2020). "PLK1 might therefore be one of the most important immune genes that contribute to biochemical recurrence in prostate cancer." (PMID 33197890, 2020). "Recent studies have shown that, in addition to inducing necroptosis in prostate cancer cells, the PLK1 inhibitor BI2536 sensitizes esophageal squamous cell carcinoma cells to cisplatin in vivo and in vitro by inhibiting the DNA damage repair and promoting pyroptosis." (PMID 33665167, 2020). "Furthermore, PLK1 expression was significantly increased in prostate cancer compared to prostatic hyperplasia." (PMID 33197890, 2020). "Network analysis revealed that PLK1 may be a key regulator of the immune-suppressive microenvironment in prostate cancer." (PMID 33197890, 2020). "Although they reported that PLK1 overexpression in prostate cancer triggers the EMT by activating CRAF/ERK signaling, it remains unclear how PLK1 induces the EMT and which factors are the main causes of PLK1-induced EMT." (PMID 31548612, 2020). "Investigators have shown that FTY720 targets Plk1 signaling in prostate cancer cells and may also affect the Wnt/beta-catenin pathway through its action on Plk1." (PMID 30969990, 2019). "As a major driving force of the EMT process in prostate cancer, PLK1 overexpression might contribute to therapeutic resistance to anti-cancer therapies through EMT." (PMID 28953239, 2017). "Consistently, PLK1 downregulation in metastatic prostate cancer cells inhibited cell motility." (PMID 28953239, 2017). "Analyses using prostate cancer cell lines, a prostate-specific PTEN-deletion mouse model, and a xenograft mouse model revealed that PLK1 is critical for PTEN-depleted cells to adapt to mitotic stress for survival, which assists the loss of PTEN-induced prostate cancer formation." (PMID 28953239, 2017). "Furthermore, we investigated the potential role of SUB1-induced PLK1 in prostate cancer invasion by using PLK1-specific siRNA pool or inhibitor volasertib." (PMID 27270442, 2016). "A future challenge is to find out how PLK1 is regulated in people with prostate cancer and whether the EMT is involved in promoting other processes in cancer cells." (PMID 27003818, 2016). "Interestingly, PLK1 and CDC25C are overexpressed in prostate cancer, and PLK1 expression correlates with high tumor grades." (PMID 24525428, 2014). "Targeting PLK1 has been shown to induce apoptosis in prostate cancer cells after radiation, therefore we investigated whether BI2536 could trigger apoptosis in our model." (PMID 24525428, 2014). "While the Warburg effect is a hallmark of various cancers, our study shows that PLK1-overexpressing LNCaP prostate cancer cells do not significantly elevate lactate secretion despite enhanced glycolysis (Fig. EV 11A), whereas C4–2-PHGDH-3D cells secret abundant lactate (Fig. EV11C)." (PMID 40475404, 2025).
prostate carcinoma (continued). "PLK1 is also a valuable molecular target for angiogenesis, and inhibition of its expression can inhibit the formation of new tubular structures in non-small cell lung cancer and prostate cancer, and enhance the chemotherapy sensitization of paclitaxel in cancer cells." (PMID 40612941, 2025). "PLK1 may play a potential regulatory role as a core gene in the development of prostate cancer." (PMID 37664042, 2023). "Therefore, we hypothesized that YTHDF1 could affect PI3K/AKT pathway activation by regulating the protein level of PLK1, thereby promoting prostate cancer tumorigenesis and metastasis." (PMID 36439881, 2022). "Bl2536, which is a small molecule inhibitor of the mitotic kinase polo-like kinase 1 (Plk1), was demonstrated to inhibit Plkl during mitotic progression and lead to mitotic catastrophe, resulting in necroptotic cell death in androgen-insensitive prostate cancer cells." (PMID 31122251, 2019). "In addition, PLK1 inhibition could potentially be a promising strategy to prevent prostate cancer dissemination." (PMID 28953239, 2017). "Additionally, SUB1 and PLK1 mRNA levels are correlated in prostate cancer cell lines." (PMID 27270442, 2016). "Our finding that PLK1 leads to the decrease of PHGDH, thus decreasing of SSP in prostate cancer, which is reminiscent of checking inosine monophosphate (IMP), the downstream purine from glucose and one carbon metabolism." (PMID 40475404, 2025). "Immunohistochemical results from the Human Protein Atlas (HPA) database suggested decreased protein expression levels of CD38 in prostate cancer tissues, while MMP11 and PLK1 showed moderate expression in both normal and cancerous tissues." (PMID 41415207, 2025). "The PLK1 inhibitor BI6727 inhibits proliferation and induces apoptosis in all three prostate cancer cell lines, consistent with previous studies." (PMID 40809688, 2025). "SHCBP1 was found to enhance prostate cancer cell development, metastasis, and mitosis, with the SHCBP1—polo‐like kinase 1 (PLK1)—CDC25C axis playing a key role in promoting tumorigenesis." (PMID 39949984, 2025). "CBX3-targeted dual BET/PLK1 inhibition amplifies the effects of CDK4/6 inhibitors by disrupting BRD4/PLK1-mediated transcription and inducing cell-cycle arrest in prostate cancer." (PMID 41583469, 2025). "PLK1 is suggested to be a key driver of EMT and metastasis in prostate cancer, gastric cancer, lung cancer, pancreatic ductal adenocarcinoma, and renal cell carcinoma." (PMID 39451218, 2024). "PLK1 also induces epithelial-to-mesenchymal transition and promotes cell motility by activating the CRAF/ERK signaling pathway in prostate cancer cells." (PMID 38355643, 2024). "Synergistic cancer cell killing by the combination of olaparib and PLK1 inhibition, using other small molecules, including BI2536 and BI6727 (volasertib), has been reported in castration-resistant prostate cancer and in HGOC cells with KRAS amplification." (PMID 39039067, 2024). "An E2F target gene signature, formed by MDX3, PLK1, EPHA10, and KIF4A, exhibited a stronger predictive power than existing signatures in prostate cancer." (PMID 37854038, 2023). "PLK1 also phosphorylates MRE11 on S649, and prostate cancer cells (U2OS) expressing phosphomimetic MRE11 have a 5-fold increased sensitivity to olaparib, both in vitro and in vivo." (PMID 36765954, 2023). "Our study identified PLK1, a key factor in the cell cycle, as the direct target of YTHDF1 in prostate cancer cells." (PMID 36439881, 2022). "The four gene signatures (MDX3, PLK1, EPHA10, and KIF4A) showed a strong correlation with prostate cancer prognosis in cases selected from TCGA database." (PMID 35495629, 2022).
prostate carcinoma (continued). "We find that MBNL1-AS1 has been reported to inhibit the progression of prostate cancer by sponging miR-181a-5p and regulating PTEN/PI3K/AKT/mTOR signaling and PTEN signaling happens to be regulated by PLK1, PAF, YB-1, TWIST, YY1, KLF4, and SALL4." (PMID 35518784, 2022). "Recent studies show that PLK1 and KIF4A as biomarkers have a high prognosis value in patients with prostate cancer." (PMID 35495629, 2022). "Our data demonstrated that overexpression of ELK1 in prostate cancer cells contributed to the transcriptional activation of YTHDF1, further resulting in aberrant regulation of PLK1/PI3K/AKT axis." (PMID 36439881, 2022). "Here, we provided evidence that PLK1-dependent phosphorylation of FOXO1 induces its nuclear exclusion and negatively regulates FOXO1′s transcriptional activity in prostate cancer (PCa)." (PMID 32704044, 2020). "A number of observations have described sensitivity of AR-resistant prostate cancer cells to death induced by certain triggers such as TWEAK, sorafenib, olaparib, and inhibition of BET proteins or PLK1, among others." (PMID 29371637, 2018). "Numerous studies have tested PLK1 inhibitors, including BI2536, as potential cancer therapeutics for advanced metastatic tumors, including prostate cancer, lung cancer, neuroblastoma, and non‐Hodgkin's lymphoma to name a few." (PMID 30414309, 2018). "The aptamer, modified A10 in the chimeras mediates cell type-specific binding to human PSMA, a cell-surface receptor expressing in prostate cancer cells, whereas, the therapeutic CRISPR/Cas9 target PLK1." (PMID 28030843, 2017). "Like in other cancers, Polo-like kinase 1 (PLK1), a serine-threonine-protein kinase enzyme, is overexpressed in prostate cancer." (PMID 34322587, 2017). "In this regard, aptamer-mediated delivery of therapeutic siRNAs against anti-apoptosis genes polo-like kinase 1 (PLK-1) and B-cell lymphoma 2 (BCL-2) has been tested in prostate cancer cells with encouraging results." (PMID 26863567, 2016). "Additionally, PLK1 is overexpressed in prostate tumors and its expression is correlated to higher tumor grades suggesting that PLK1 might be a potential therapeutic target for prostate cancer." (PMID 24525428, 2014). "Several of the transcripts identified in the CTCs have been correlated with aggressive behavior in localized prostate cancer (e.g. PLK-1, TOP2A) so it is interesting to observe these markers in cells from patients with highly advanced prostate cancers." (PMID 23145101, 2012). "The positive control siRNAs targeting known key regulators of the mitotic progression as well as prostate cancer cell proliferation, KIF11 and PLK1, were able to significantly decrease cell viability confirming thus transfection efficiency." (PMID 22761906, 2012). "It has also been found that menthol arrests the cell cycle at the G0/G1 phase in androgen-independent prostate cancer cells and the G2/M phase in PC3 prostate cancer cells by downregulating CDK2, 4, and six and downregulating downstream signaling of polo-like kinase 1 (PLK1), respectively." (PMID 40458805, 2025). "Clinically, PLK1 is established as a prognostic marker and a therapeutic target for the majority of solid, blood, and metastatic cancers, including gastric cancer 19, NSCLC 20, colorectal cancer 48, and prostate cancer." (PMID 36793862, 2023). "Furthermore, it prevented KDM4B from binding to the polo-like kinase-1 (PLK1) promoter, showing a possible mechanistic treatment approach to prostate cancer and tumors expressing high levels of KDM4B/PLK1." (PMID 37218871, 2023). "Indeed, high expressions of CDC20, PLK1 and CDK1 correlate with prostate cancer occurrence and worse biochemical recurrence survival rates." (PMID 37509260, 2023). "In our studies, we suggested that m6A modification of PLK1 mRNA could be recognized by m6A “reader” YTHDF1, which then induced PLK1 translational rate in prostate cancer, thus promoting prostate cancer progression." (PMID 36439881, 2022).
prostate carcinoma (continued). "The expression of PLK1 is high in diverse leukemias and carcinomas, including NSCLC, head and neck, esophageal, pharynx, liver, breast, colon, ovarian, stomach, pancreatic, and prostate cancers, and melanoma." (PMID 35379935, 2022). "PLK1 and MELK have been suggested to be potential targets in prostate cancer." (PMID 33632199, 2021). "PLK1 was positively correlated with CD163 in prostate cancer (Pca) samples (r=0.69, p<0.01), but not in benign prostatic hypertrophy (BPH) samples (r=0.12, p=0.63)." (PMID 33197890, 2020). "In a therapeutic in vivo setting, profound anti-tumor effects in a prostate carcinoma xenograft mouse model are observed upon systemic application of complexes for survivin or PLK1 knockdown, in the absence of in vivo toxicity." (PMID 31726756, 2019). "Our recent study showed that PLK1 overexpression induces EMT and promotes cell motility and invasiveness in human prostate epithelial cells; whereas the attenuation of PLK1 expression reduces the invasiveness of human prostate cancer cells." (PMID 28953239, 2017). "Additionally, we validated both PLK1 mRNA and protein levels across benign, prostrate carcinoma and metastatic prostate cancer tissues by qPCR and immunoblot analysis, respectively, which confirmed the direct correlation between SUB1 and PLK1." (PMID 27270442, 2016). "Thus, these consolidated observations underscore a downstream role for PLK1, C-MYC and CDKN1B in SUB1-mediated prostate cancer cell proliferation and invasion." (PMID 27270442, 2016). "Indeed, overexpression of PLK1 induced EMT-like alterations in prostate epithelial cells, whereas PLK1 knockdown restored epithelial features of invasive prostate cancer cell lines." (PMID 27003818, 2016). "This was also the case for luteolin regulation of the PLK1 gene in PC-3 human prostate cancer cells which are not estrogen-dependent." (PMID 21731475, 2011). "Notably, PLK1 was highly expressed in the prostate tumors compared to the adjacent tissues, and its elevated expression correlated with poor overall survival (OS) and disease‐free survival (DFS) in various cohorts of prostate cancer patients." (PMID 40536697, 2025). "However, the molecular mechanism by which PLK1 regulates prostate cancer progression has not yet been elucidated." (PMID 36439881, 2022). "Moreover, PLK-1 expression was decreased in the prostate cancer cell line treated with the liposomes, but not in the untreated control." (PMID 34458758, 2020). "The role of PLK1 in prostate cancer is not clear at present." (PMID 33197890, 2020). "Previously, numerous studies addressed the role of PLKs for proliferation of prostate cancer cells and for tumor growth in the prostate, while the present study may be the first suggesting expression and a function of PLK1 in non-malignant prostate tissue." (PMID 29962965, 2018). "Furthermore, SUB1 overexpression elevated PLK1 and C-MYC expression, and reduced CDKN1B expression, showing SUB1 dysregulation triggers alterations in critical oncogenes and tumor suppressors in prostate cancer." (PMID 27270442, 2016). "However, it is not clear how PLK1 phosphorylation is regulated in prostate cancer bone metastasis." (PMID 39949984, 2025). "Our findings highlight novel non-canonical functions of PLK1 as a key regulator of EMT and cell motility in normal prostate epithelium and prostate cancer." (PMID 27003818, 2016). "We report that apigenin affects prostate cancer cells at G2 phase rather than at M phase with concomitant down-regulation of the regulators that govern G2-M transition at the transcriptional level including CDK1, CyclinB1, Polo-like kinase 1 (PLK1) and Aurora A." (PMID 35670862, 2022).
lung carcinoma (98 papers, 2004 to 2026). "Initially, the survival outcomes validated that the clinical relevance of PLK1 overexpression is more highly associated with poor prognosis in breast and lung cancers than other types." (PMID 41404416, 2025). "As our findings suggested a stronger association of PLK1 mutations with concomitant mutations in CRC than in lung cancer, we further performed comparison of other genomic features between PLK1‐mutated and wild‐type CRCs." (PMID 38887977, 2024). "Alongside its intricate associations with AHR and PLK1, a comprehensive exploration of these multifaceted aspects promises to enhance our comprehension of lung cancer etiology, ultimately translating into improved clinical care for patients." (PMID 37988371, 2023). "Specifically in NSCLC, PLK1 overexpression promotes lung cancer progression and is associated with poor patients’ outcomes." (PMID 37988371, 2023). "In lung squamous cell carcinoma, PLK2/3/4 methylation was dramatically associated with longer survival time of lung cancer, whereas PLK1 methylation was significantly associated with shorter survival time." (PMID 34080290, 2021). "PLK1 overexpression is thought to be associated with chemotherapy resistance, and inhibition of PLK1 may improve the sensitivity of lung cancer cells to chemotherapeutic agents." (PMID 40355412, 2025). "Our results indicated that global methylation of PLK1/2/3/4 was obviously associated with lung cancer patients' prognosis and they may be exploited as potential targets for lung cancer therapy." (PMID 34080290, 2021). "Additionally, the Human Protein Atlas resource revealed high expression of BIRC5 or PLK1 to be associated with poor survival in renal, liver, and lung cancer patients and high expression of ROCK1 to be a marker of unfavorable prognosis in pancreatic cancer." (PMID 31523390, 2019). "rs57973275 is located in the 3 ‘-UTR region, and studies have shown that targeting this region can inhibit the expression of PLK1, thereby inhibiting the progression of lung cancer." (PMID 40612941, 2025). "Immunotherapies using NPs to target programmed death–ligand 1 (PD-L1) and polo-like kinase 1 (PLK1) have shown the potential of multitargeted approaches using markers overexpressed by tumor cells in lung cancer treatment." (PMID 40067370, 2025). "More specifically, previous studies have demonstrated the contribution of overexpressed PLK1 to cancer development in mouse models of lymphoma and lung cancer." (PMID 41284701, 2025). "In lung cancer, PLK1 inhibits DC maturation and T-cell enrichment.Moreover, PLK1 expression is positively correlated with myeloid-derived suppressor cells (MDSCs) and regulatory T cells." (PMID 40612941, 2025). "Based on data from TCGA, we found that lung cancer patients with high expression of PLK1 exhibited poorer survival (P < 0.05) compared to those with low expression of PLK1 after receiving chemotherapy." (PMID 40355412, 2025). "We further found that the expression of TSG6, CD44, CD68, and CD163 (marker of TAMs) is elevated in metastatic lung cancer tissues of mice driven by active PLK1." (PMID 40860188, 2025). "Survival analysis revealed that overexpression of CDK1, PLK1, AURKA, KIFC1, and KIF2C was associated with a statistically significant unfavorable overall survival in patients with lung cancer." (PMID 40232858, 2025). "Overexpression of PLK1 and NRP1 correlate with enhanced proliferative activity in lung cancer cells, thus the development of dual-target PLK1/NRP1 inhibitors holds great therapeutic promise." (PMID 40820676, 2025). "To investigate the impact of PLK1 on lung cancer TME, we designed a workflow to perform the scRNA-seq using our KP and KPP mouse models, which we previously reported." (PMID 38885192, 2024).